RPSAP11 (ribosomal protein SA pseudogene 11)
Synonyms: LAMR; LAMRP1; LAMR1P11; LAMRL1; RPSA_9_357
Gene: Processed pseudogene on chromosome 3 (32,190,747 to 32,191,627, forward strand). Ensembl gene ENSG00000237433.
Diseases named in the same sentence as RPSAP11 in open-access papers:
RPSAP11 is named in the same sentence as 1 disease in open-access papers, as found by Europe PMC text mining. Sharing a sentence is not in itself a finding about the gene and the disease.
RPSAP11 shares sentences with these, for which no sentence is quoted: lung carcinoma (1 paper).